MUC16 (mucin 16, cell surface associated)
Diseases named in the same sentence as MUC16 in open-access papers (continued):
Sharing a sentence is not in itself a finding about the gene and the disease.
ovarian carcinoma (continued). "Following the release of antibody-bound nanomicelle from the hydrogel, said nanomicelle targeted specific MUC16 antigens over-expressed on ovarian carcinoma cells within the ascitic fluid and within neoplastic nodules at distant sites within the peritoneal cavity." (PMID 30287783, 2018). "MUC16 is overexpressed in ovarian cancer and plays important roles in invasion and metastasis." (PMID 29708979, 2018). "The anti-MUC16 antibody conjugated nanomicelles has great potential in improvement of tumor selectivity, eliminating/reducing the tumor load, while improving the recovery and long term survival rate of most patients suffering from ovarian cancer." (PMID 30287783, 2018). "Indeed, some of the most common clinically used biomarkers for cancer diagnosis and monitoring are glycoproteins, and are known to be aberrantly glycosylated in cancer (e.g., PSA for prostate cancer; MUC16 for ovarian cancer; and SLea for pancreatic cancer)." (PMID 28672878, 2017). "MUC16, also known as carcinoma antigen 125, is a prominent biomarker of ovarian cancer." (PMID 28177878, 2017). "CA125 (MUC16) levels can rise months to years prior to conventional diagnosis of ovarian cancer." (PMID 26918940, 2016). "An ADC against MUC16 is in development by Genentech, primarily for the treatment of ovarian cancer." (PMID 26700623, 2016). "MUC16 is the gold standard biomarker in diagnosing and monitoring ovarian cancer patients." (PMID 27382435, 2016). "Furthermore, it was substantially more potent than Meso-TR3 and TR3 in vitro and in a preclinical xenograft model of MUC16-dependent ovarian cancer." (PMID 27120790, 2016). "Mesothelin interacts with CA125/MUC16 ovarian cancer antigen, and this interaction has been hypothesized to play a role in metastasis of ovarian cancers." (PMID 26931187, 2016). "While the most proximal 114 amino acid fragment of MUC16 was sufficient to transform 3T3 cells and enhance the invasion potential of the A2780 human ovarian cancer cells, the minimal part of the 114 amino acid MUC16 protein fragment responsible for transformation was still uncertain." (PMID 25965947, 2015). "The impact of MUC16 on transformation and tumor aggressiveness in the experimental models led us to re-examine the link between genetic alterations in MUC16 and the outcomes in ovarian cancer." (PMID 25965947, 2015). "The ovarian cancer antigen, MUC16, is over-expressed by a majority of ovarian cancers." (PMID 25890361, 2015). "However, recent studies have shown that mesothelin binds to the cell surface mucin, MUC16 (CA-125), which is commonly used as a marker to follow patients with ovarian cancer." (PMID 25502863, 2015). "MSLN may aid in the peritoneal implantation and metastasis of tumors through its interaction with CA125 (also known as MUC16), an ovarian cancer antigen." (PMID 25883990, 2015). "Targeted immune strategies toward CA125 and MUC16 are active areas of research in ovarian cancer and any potential breakthroughs could possibly be applicable in treating ES." (PMID 26347853, 2015). "Furthermore, vaccines and antibodies against mucins (MUC16) can limit tumor metastasis in ovarian carcinoma." (PMID 26356073, 2015). "and outperforms MUC16 in identifying patients with early stage ovarian cancer." (PMID 26509158, 2015). "Therefore, we examined the association between a targeted set of single nucleotide polymorphisms (SNPs) in MUC16 (rs2547065, rs1559168, rs12914471, rs2121133) and MUC1 (rs2070803, rs4072037, rs1045253) in relation to ovarian cancer risk and survival." (PMID 24551091, 2014). "In agreement, reduction of MUC16 expression has been related with advanced ovarian cancer." (PMID 25261375, 2014). "MUC16 knockdown sensitizes ovarian cancer cells to apoptosis induced by genotoxic drugs." (PMID 24690311, 2014).
ovarian carcinoma (continued). "We genotyped germline variants of MUC16 (rs2547065, rs1559168, rs12984471, rs2121133) and MUC1 (rs2070803, rs4072037, rs1045253) using samples collected from 758 ovarian cancer cases and 788 controls enrolled in the New England Case-Control Study between 2003 and 2008." (PMID 24551091, 2014). "Examples of cancer biomarkers routinely used in the clinic include α-fetoprotein (AFP) for diagnostics and management of testicular cancer, MUC16 (cancer antigen 125 or CA-125) for ovarian cancer, ERBB2 (HER2) protein for breast cancer, and prostate specific antigen for prostate cancer." (PMID 25521819, 2014). "MUC16 is a mucin protein overexpressed by most human ovarian epithelial cancers." (PMID 24690311, 2014). "For example, Rump and colleagues showed that binding of MUC16 to membrane-bound mesothelin mediated cancer cell adhesion in ovarian cancer and that the mesothelin-MUC16 interaction might result in the intraperitoneal dissemination of tumors." (PMID 24988079, 2014). "Women with the variant allele of MUC16 SNP, rs2547065, especially those who were homozygous had an elevated risk for ovarian cancer; but this association was not confirmed in an independent dataset." (PMID 24551091, 2014). "In this context, a combination of TRAIL with small molecules that block cell surface localization or the function of the intracellular domain of MUC16 might prove more effective in killing TRAIL resistant ovarian cancer cells." (PMID 24690311, 2014). "While MUC16 is well known as a biomarker in ovarian cancer, its expression pattern in pancreatic cancer (PC), the fourth leading cause of cancer related deaths in the United States, remains unknown." (PMID 22066010, 2011). "Apart from its importance in understanding the biological role of MUC16, the data also suggests that sMUC16 binding to immune cells may serve as a novel strategy for the detection and monitoring of ovarian cancer." (PMID 20497550, 2010). "The immune protection provided by MUC16 may lead to selective survival of ovarian cancer cells that are more efficient in metastasizing within the peritoneal cavity and also at overcoming anti-tumor innate immune responses." (PMID 20089172, 2010). "However, we and others have shown that it binds to MUC16, which facilitates the metastasis of ovarian cancer cells to the peritoneal cavity." (PMID 20350313, 2010). "In addition, a thorough study of MUC16 expressed in mouse models for ovarian cancer will also aid in understanding its physiological roles." (PMID 19538730, 2009). "Several studies have shown the importance of CA125/MUC16 in ovarian cancer diagnosis." (PMID 20034397, 2009). "Furthermore, the initial identification and characterization of murine Muc16 is a vital preliminary step in the development of effective murine models of human ovarian cancer." (PMID 19538730, 2009). "Immune suppressive properties of MUC16, along with its expression in ovarian cancer cells and fetal periderm, suggest a role for MUC16 in immune evasion of ovarian cancer cells from the host immune system and in fetal tolerance from maternal immune rejection during early pregnancy." (PMID 19262696, 2009). "The performance of the MUC16/WFDC2 combination marker clearly varied with ovarian cancer histology: the percentage of cases correctly classified was 86% (38/44) for serous cases, 83% (5/6) for endometrioid cases, 17% (1/6) for mucinous cases and 0% (0/5) for clear cell cases." (PMID 18612378, 2008). "Therefore, it is reasonable to speculate that a TanCAR combining PD-1 and anti-MUC16 could be an effective strategy against epithelial ovarian cancer." (PMID 40092990, 2025). "Similarly to MUC16 in ovarian cancer, these mucins are all part of the membrane-bound mucin family, which possesses a more significant number of O-glycosylation sites and more tandem repeats, the former being a shared feature of secreted and membrane-bound mucins." (PMID 39767713, 2024).
ovarian carcinoma (continued). "Notably, OVA1® is a United States (US) Food and Drug Administration (FDA) approved test, which includes apolipoprotein A-I (APOA1), transthyretin (TTR), transferrin (TF), β2-microglobulin (B2M), along with MUC16, and has demonstrated effectiveness in detecting early-stage ovarian cancer." (PMID 40836974, 2024). "However, the potential effectiveness of CAR-T cell therapy that targets MUC16 in ovarian cancer cells is unknown." (PMID 38637885, 2024). "Since a stronger correlation was observed between MUC16 and neutrophils compared to macrophages, with a stronger correlation to inflammatory pathways, we speculated that MUC16 might be involved in neutrophil-induced inflammation in ovarian cancer." (PMID 37644468, 2023). "In next-generation immunotherapy, anti-MUC16 scFv (4H11-scFv) was employed on a bispecific T-cell engagers (BiTEs), which displayed redirected T-cell immunologic synapses and suppressed metastatic potential of epithelial ovarian cancer in an in vivo mouse model." (PMID 37509200, 2023). "In addition, mucin-related tumor markers have been widely used in clinical practice, for example, MUC16 (CA125) has been widely used as a marker for ovarian cancer; SLea (also called CA19-9) is a marker for pancreatic cancer; MUC1 (CA153) is a biomarker for breast cancer." (PMID 36429094, 2022). "Interestingly, a correlation between therapeutical response and the quantity of MUC16 in ovarian cancer patients could be observed in two clinical trials." (PMID 36230626, 2022). "Even though signaling pathways via the MUC16 cytoplasmic domain are largely unknown, a strong correlation between the serum CA125/MUC16 level and ovarian cancer prognosis also suggests that MUC16 is a potential therapeutic target for the treatment of ovarian cancer." (PMID 34681277, 2021). "However, MUC16 is overexpressed in 80% of ovarian cancers compared to normal ovarian tissue, indicting it might serve as a potential treatment target." (PMID 33391401, 2021). "MUC4 could also be used in combination with MUC16 for detection of advanced ovarian cancer." (PMID 34336844, 2021). "Indeed, MUC16 (cancer antigen 125, CA 125) is used in clinics to diagnose and predict prognosis in ovarian cancer patients, but it is also upregulated in a large percentage of digestive tract adenocarcinomas and has been proposed as a prognostic marker for gastrointestinal cancers." (PMID 32293552, 2020). "Among the potential MGL ligands, we identified glycoproteins that are linked to ovarian cancer progression, such as IGFBP7, MUC16, and VCAN, suggesting that MGL expressed by DCs may exert its immunoregulatory role by interacting with distinct cellular and matrix components." (PMID 33019700, 2020). "Because we had evidence that NF-κB-mediated transcription is stimulated by ascites in ovarian cancer cell lines (Lane, unpublished data), and because NF-κB is a downstream effector of several cytokines, we assessed the role of NF-κB in ascites-induced stimulation of MUC16 expression and release." (PMID 31039761, 2019). "Because ovarian cancer ascites is an inflammatory environment that contains a variety of cytokines, chemokines and growth factors, we hypothesized that ascites could stimulate the expression of MUC16 and its release by HPMCs." (PMID 31039761, 2019). "In addition to ovarian cancer, MUC16 up-regulation may be involved in the development and progression of pancreatic cancer." (PMID 29552305, 2018). "In addition to ovarian cancer, MUC16 may be a candidate biomarker for air pollution-related lung cancer." (PMID 29552305, 2018). "Moreover, MUC16 contributes to the ovarian cancer growth and its metastatic activity." (PMID 29588543, 2018). "Chemo-treatment with AF(D)NMs significantly inhibited growth of and transcoelomic metastasis of EOC (via reducing MUC16 antigen expression on tumor xenografts) and reduced the production of ascitic fluid, thereby possessing potential for increasing longevity in patients with ovarian carcinoma." (PMID 30287783, 2018).
ovarian carcinoma (continued). "However, the relationship between the MUC16 cytoplasmic or membranal expression and ovarian cancer development remains unclear." (PMID 29542355, 2018). "Our strategy was dual targeting of ovarian cancer via a MUC16 promoter trigger and FSHR mediation, which could enhance therapeutic specificity by avoiding the expression of passive-uptake shRNA drugs in non-cancer cells and which could reduce off-target effects." (PMID 29542355, 2018). "Regulation of MUC16 expression through NFκB could aid in early detection of ovarian cancer." (PMID 26918940, 2016). "And finally, another important aspect regarding the mesothelin/MUC16 interaction is its potential contribution to homotypic (tumor cell-tumor cell) and heterotypic (tumor cell-mesothelial cell) cell interactions, especially important for the peritoneal spread in ovarian cancer patients." (PMID 27120790, 2016). "Additional work of the precise mechanisms initiating MUC16 signaling, the effects of MUC16 binding to stromal elements, and the identification of the key molecular partners of cell surface MUC16 are likely to further enhance our understanding of ovarian cancer biology." (PMID 25965947, 2015). "A clearer understanding of the mechanisms underlying MUC16 intracellular signaling could lead to the development of novel approaches to enhance the efficacy of TRAIL for the treatment of ovarian cancer." (PMID 24690311, 2014). "However, there may be effects of MUC16 rs12984471 on survival and MUC1 rs4072037 on risk for histologic types of ovarian cancer other than invasive serous." (PMID 24551091, 2014). "Therefore, cell surface expression of E-cadherin and CA125/MUC16 may be functionally important during ovarian carcinoma formation." (PMID 21326240, 2011). "Additionally, recent studies have shown the role of MUC16/CA125 in ovarian cancer metastasis." (PMID 20034397, 2009). "However, biological functions of MUC16 in normal physiology as well as in pathological conditions such as ovarian cancer still remain unknown." (PMID 19262696, 2009). "Ubamatamab (REGN4018) is a bsAb that targets MUC16, also known as CA-125, and CD3, thereby redirecting T-cells toward MUC16-expressing ovarian cancer cells." (PMID 41211166, 2025). "When antibody-loaded paclitaxel nanoparticles and anti-MUC16 nanomicelles have been used to target mesothelin and MUC16 (CA125), ovarian cancer targeting ability and tumour uptake were increased, and systemic toxicity was reduced." (PMID 41514600, 2025). "Collectively, the evidence implicates MUC16 and TGF-β as central regulators of NK cell dysfunction in ovarian carcinoma, emphasizing their value as immunotherapeutic targets to restore innate antitumor responses." (PMID 41567203, 2025). "Gubbels and colleagues reported that NK cells more effectively eliminate ovarian cancer cells with low csMUC16 expression, which retain activating ligands for DNAM-1 and NKG2D receptors, highlighting MUC16’s critical role in immune escape." (PMID 41567203, 2025). "Regarding ovarian carcinoma and cysts, MSA (UMA1) and MUC16 (CA125) can present equivocal test scenarios." (PMID 40699805, 2025). "Among these biomarkers, the CA125 antigen, also known as mucin 16 (MUC16), is widely used for detecting epithelial ovarian cancer." (PMID 41149076, 2025). "To evaluate SYCP2 functionally, we performed SYCP2 knockdown in ovarian cancer cell lines with high SYCP2 expression, including OVCAR8 and SKOV3 (both WT and MUC16+)." (PMID 40918650, 2025). "In ovarian cancer, bispecific CAR-T targeting PDL1 and MUC16 have been used to overcome on-target off-tumor toxicity." (PMID 39844819, 2025). "The expression of specific antigens, such as FRα, MUC16/CA125, and TROP2 in ovarian cancer cells has led to the development of novel ADCs with improved efficacy and safety profiles." (PMID 40722601, 2025). "In ovarian cancer, bispecific PDL1/MUC16 CAR-T cells demonstrated a significant therapeutic effect in an OVCAR-3 tumor mouse model." (PMID 39844819, 2025).
ovarian carcinoma (continued). "Another independent study identified FGG, MUC16, and APOA4 as key EV proteins capable of distinguishing malignant ovarian tumors from benign cystadenomas or healthy tissue." (PMID 41294748, 2025). "While MUC1, MUC4, MUC15, MUC16, MUC17, and MUC21 are all potential candidate biomarkers for glioma, the extensive research on MUC1 and the current clinical application of MUC16 in ovarian cancer highlights their promise as therapeutics for glioma." (PMID 39767713, 2024). "The cleavage of MUC16 forms independent bimodular fragments, the shed tandem repeat sequence which circulates as a protein bearing the ovarian cancer biomarker (CA125) and a proximal membrane-bound component which is critical in MUC16 oncogenic behavior." (PMID 38374055, 2024). "Meanwhile, MUC16 has been extensively researched as a biomarker in ovarian, pancreatic, and bladder cancer, with the clinical application of CA125 in ovarian cancer, where MUC16 is FDA-approved as a biomarker for monitoring ovarian cancer recurrence." (PMID 39767713, 2024). "The regular and close-packed display of MUC16 peptide on the surface of HPV16 VLPs is intended to safely break tolerance and thus generate a robust MUC16-antibody response targeting ovarian cancer cells." (PMID 38225646, 2024). "Chekmasova’s team developed a range of CARs aimed at the extracellular domain of MUC16 (MUC-CD), resulting in T cells equipped with these CARs showing marked cytotoxicity against MUC-CD, thus effectively managing ovarian cancer." (PMID 38361923, 2024). "The MUC16 gene and its homologous antigen carbohydrate antigen 125 (CA125) have long served as classic markers for ovarian cancer." (PMID 38758220, 2024). "Siglec-9, the receptor of MUC16, had strong correlations with markers of neutrophil ITGAM, ITGB2, FCGR1A, FCGR2A, FCGR3A, analyzed with TCGA-OV database and ovarian cancer tissue RNA sequencing data." (PMID 37644468, 2023). "Clinically, few trials investigating CAR T-cell treatments for ovarian cancer are under way, with common targets including MSLN, FSHR, MUC16, and HER2." (PMID 36166071, 2023). "The most commonly used serum biomarker for ovarian cancer is CA 125 (Carcinoma antigen 125, also known as mucin 16 or MUC16), which was initially used to monitor ovarian cancer patients during therapy." (PMID 36900385, 2023). "A refinement of this study was achieved through the use of proximity-ligation assay (PLA), in which aberrant glycoforms (Tn, STn, and T) of MUC16 and MUC1 in ovarian cancer tissue were detected." (PMID 37455827, 2023). "One of the most widely used serum biomarkers for ovarian cancer is CA125, also known as Mucin-16(MUC16), which is a member of the mucin family glycoproteins." (PMID 37958227, 2023). "Circulating N-terminal MUC1 (CA15-3) is used for monitoring the clinical course in breast cancer 21, and circulating MUC16 (CA125) is used for detecting early-stage disease and monitoring the clinical course in ovarian cancer." (PMID 37324940, 2023). "MUC16 (CA125) is a selectin ligand expressed in metastatic pancreatic cancer cells and epithelial ovarian cancer cells." (PMID 35464064, 2022). "A panel composed of three proteins (FGG, MUC16, and APOA4) in serum sEVs showed remarkable performance for ovarian cancer screening in populations." (PMID 35954383, 2022). "Through univariate and multivariate logistic regression analyses, a novel model comprising three proteins (fibrinogen gamma gene (FGG), mucin 16 (MUC16), and apolipoprotein (APOA4)) was established to screen patients with ovarian cancer." (PMID 35954383, 2022). "REGN4018, a T-cell engaging bsAb targeting MUC16 × CD3, is currently being investigated in a clinical trial for ovarian cancer (NCT03564340)." (PMID 35836956, 2022). "Blocking CA125/MUC16 and mesothelin binding was able to restore DKK1 levels and prevent ovarian cancer metastasis." (PMID 35326701, 2022).